ENSG00000207407
Synonyms: LOC124900310
Gene: Small nucleolar RNA gene on chromosome 11 (19,591,156 to 19,591,291, reverse strand). Ensembl gene ENSG00000207407.
Gene Ontology:
Biological process: RNA processing
Cellular component: nucleolus
Homologues: Paralogues in human: SNORA1 (80% identical), SNORA1B (79% identical).